JAK1 (Janus kinase 1)
Diseases named in the same sentence as JAK1 in open-access papers (continued):
Sharing a sentence is not in itself a finding about the gene and the disease.
COVID-19 (continued). "In conclusion, transcription and activation of pathogenic complement can be normalized in epithelial cells using drugs that target JAK1, CFB or the virus itself and combinations of these may be therapeutically beneficial in treating COVID-19." (PMID 33827897, 2021). "As ruxolitinib inhibits both JAK1 and JAK2, it may be a rather promising candidate to be used in COVID-19 induced hyperinflammatory diseases." (PMID 34385593, 2021). "Baricitinib, a selective inhibitor for JAK1 and JAK2 commonly used for rheumatoid arthritis, has shown in combination with an antiviral, known as remdesivir, to decrease recovery time for patients with COVID-19, particularly those on high flow oxygen." (PMID 34248990, 2021). "In a recent clinical study of individuals with COVID-19, ruxolitinib, a JAK1/2 inhibitor, was not significantly superior to placebo in terms of clinical parameters, although faster recovery from lymphopenia was observed." (PMID 33584343, 2021). "Further, DTP-based retrieval of approved drugs showed that combination therapy with sorafenib, sunitinib, nintedanib (PDGFRB), sunitinib, nintedanib, ruxolitinib (JAK1), and ceritinib (IGF1R) could be helpful to diabetic COVID-19 patients." (PMID 34067609, 2021). "It means that SARS-CoV-2 infection may enhance the production of cytokines and aggravate the pulmonary inflammation through the JAK1 related signaling pathways, thus leading to an increased mortality rate in LUAD patients with COVID-19." (PMID 33323549, 2020). "Some physicians suggest tofacitinib, a small molecule compound target JAK1 and JAK3, could be applied in the treatment of COVID-19, and tofacitinib success in treating a COVID-19 patient complicated with ulcerative colitis." (PMID 32754163, 2020). "This suppression not only promotes viral replication since inhibition of the IFN signaling using a JAK1/2 inhibitor could restore the replication defect of the Nsp15 mutant, but may also contribute to the delayed IFN response observed in COVID-19 patients (52, –, 54)." (PMID 40838727, 2025). "Furthermore, Ruxolitinib, a JAK1/JAK2 inhibitor acting downstream of JAK-dependent chemokines/cytokines such as IFN-γ, IL-1β, IL-6, TNF, G-CSF, CXCL9, and CXCL10, has shown promising results in treating COVID-19." (PMID 35269470, 2022). "Considering that fedratinib/pacitinib spare antigen-specific T-cell activity and minimize opportunistic infections, selective JAK2 inhibitors could be initially trialed rather than broader JAK1/2 inhibitors in the treatment of COVID-19 CRS." (PMID 36111104, 2022). "Decreased JAK1 expression in LUAD patients was associated with unfavorable prognosis, but it was not clear that whether JAK1 was associated with increased mortality rate and severity in LUAD patients with COVID-19." (PMID 33323549, 2020). "Therefore, it is reasonable to infer that baricitinib, a JAK1/2 inhibitor, may also play an anti-fibrosis role in IPF patients infected with COVID-19, and baricitinib can be developed as a drug candidate to effectively prevent pulmonary fibrosis after COVID-19 infection." (PMID 36903446, 2023). "JAK1 and JAK2, non-receptor tyrosine kinases involved in multiple stages of cell development and epigenetic modification processes, impact the inflammatory process and virus entry events in COVID-19." (PMID 39130417, 2024). "Baricitinib inhibits Janus kinase 1/2 (JAK1/2), which is essential, although not restricted, to IFNAR signaling, and early evaluation in combination with remdesivir in hospitalized patients with COVID-19 yielded promising results, with significantly reduced mortality." (PMID 36083891, 2022).
breast cancer (84 papers, 2007 to 2026). A primary or metastatic malignant neoplasm involving the breast. "IL-11 activates osteoclastogenesis in breast cancer bone metastasis-associated osteolysis through the JAK1/STAT3/c-Myc pathway." (PMID 37199584, 2023). "Demodulation of Jak, stat 3 and Akt signalling along with MAP kinase pathway cause paclitaxel resistance by STAT3 in breast cancer, and also the basal activity of JAK1/STAT1 and JAK1/STAT3 signalling is higher in chemo resistant cells." (PMID 36415633, 2022). "With respect to these tumor mutations, we found some subtle differences among breast cancer patients with different BMIs; for example, more JAK1 mutations were found in underweight patients." (PMID 33868999, 2021). "JAK1 was associated with the poor survival of patients with breast cancer; JAK1 knockdown by siRNA or inhibitors can lead to the arrest of cell grow and apoptosis." (PMID 33323549, 2020). "Here, we evaluated the association between tumor JAK1 mRNA levels and breast cancer patients’ prognosis in public databases such as the Kaplan-Meier plotter, PrognoScan database, and the Human Protein Atlas database." (PMID 31790361, 2019). "Our findings shed light on the important role of JAK1 in breast cancer as well as providing a potential relationship and an underlying mechanism between JAK1 and tumor-immune interactions." (PMID 31790361, 2019). "JAK1 is expressed in immune cells and TILs which have been associated with favorable breast cancer prognosis." (PMID 31790361, 2019). "Eight cohorts (GSE6532-GPL570, GSE9195, GSE12093, GSE11121, GSE9893, GSE1456-GPL96, GSE3494-GPL96, GSE7390) including different stages of breast cancer showed that high JAK1 expression was associated with a favorable prognosis." (PMID 31790361, 2019). "Jak1 mutations were previously reported in various cancers, including leukemia, lung cancer, breast cancer, and hepatocellular carcinoma." (PMID 29735884, 2018). "Similarly, Janus kinase 1 (JAK1) mutations have been implicated in multiple cancers, including leukemia, breast cancer, lung cancer, and liver cancer." (PMID 40344393, 2025). "JAK1 mutations might play a vital role in the progression of breast cancer in underweight patients, but further studies are needed before reaching a conclusion." (PMID 33868999, 2021). "JAK1 mutations might play a vital role in the progression of breast cancer in underweight patients, and this needs further analysis." (PMID 33868999, 2021). "Moreover, a lower JAK1 expression is associated with T-cell infiltration and a poor prognosis in breast cancer." (PMID 33323549, 2020). "Association between JAK1 mRNA and clinicopathological characteristics in breast cancer patients." (PMID 31790361, 2019). "Whether JAK1 levels in breast cancer tissues are associated with tumor immune infiltrates and clinical outcomes has not been evaluated." (PMID 31790361, 2019). "However, we have previously reported that short-term suppression of either pSTAT5 or JAK1/2 activity can restore the apoptosis anticancer barrier and reduce mammary tumor risk in mouse models." (PMID 29778097, 2018). "Therefore, it is conceivable that low JAK1 expression could be a risk factor for a poor prognosis in breast cancer patients." (PMID 31790361, 2019). "Ruxolitinib, a JAK1/2 inhibitor, and Calcitriol (1,25-dihydroxy vitamin D3), the active form of vitamin D, have synergistic effects in breast cancer." (PMID 40662801, 2025). "The co-occurrence of JAK1 and JAK3 mutations with other genetic alterations has also been observed in solid cancers, such as breast cancer." (PMID 37140667, 2023).
breast cancer (continued). "IL-11 is essential for promoting osteolysis in breast cancer bone metastasis via RANKL-independent osteoclastogenesis by activating the JAK1/STAT3 signaling pathway." (PMID 37199584, 2023). "The scores for JAK1 in tumour cytoplasm (p = 0.022) and stromal expression (p = 0.045) were significantly different when compared across molecular subtypes of breast cancer." (PMID 37199043, 2023). "We conclude on a novel mechanism whereby opioid-triggered breast cancer metastasis occurs via oncogenic JAK1/2-STAT3 signaling to promote epithelial-mesenchymal transition." (PMID 33465556, 2021). "JAK1 modulates oncogenic activation of STAT3 in mammary cancer cells driven by ERBB2 receptor tyrosine kinase signaling." (PMID 34455105, 2021). "Taken together, we show here for the first time that DOR-triggered migration and metastasis of breast cancer cells acts via oncogenic JAK1/2-STAT3 signaling, promoting breast cancer progression potentially through increased EMT." (PMID 33465556, 2021). "In a proof-of-principle experiment, we used the dual recombinase approach in this study to conditionally delete JAK1 in KRAS-transformed mammary cancer cells." (PMID 34675248, 2021). "In a previous study, we found that the levels of JAK1 mRNA were correlated with prognosis and immune infiltration in breast cancer." (PMID 33868999, 2021). "Candidate predictive biomarkers to date include elevated CRP in pancreatic and breast cancers, PTPRT/D mutations in HNC, and a JAK1 S703I mutation in HCC, and assessments of biologically plausible biomarkers that predict clinical responses are needed." (PMID 33521321, 2020). "Ruxolitinib is a tyrosine kinase inhibitor that selectively inhibits Jak1 and Jak2 signaling and is being evaluated in multiple breast cancer clinical trials for its chemotherapeutic effects." (PMID 33019728, 2020). "Clinical trials testing of JAK1 inhibitors in advanced solid tumors, including breast cancer, are under way." (PMID 31790361, 2019). "In basal-like breast cancer, JAK1 expression levels were positively correlated with infiltrating levels of CD4+ T cells, neutrophils, and dendritic cells." (PMID 31790361, 2019). "Strong correlations were rare To verify the results of the database analyses, we further explored the correlation between JAK1 mRNA levels and TILs using our own breast cancer specimens." (PMID 31790361, 2019). "To further evaluate JAK1 expression of breast cancer, we examined JAK1 expression using TCGA RNA-sequencing data." (PMID 31790361, 2019). "(B, C) A combined panel of selected breast cancer and near-normal cell lines was reverse-transfected with 10 nM pooled JAK1, JAK2, STAT3 or KRAS siRNAs and cell viability determined after 6 days." (PMID 30777101, 2019). "To further elucidate the pathway dependency in a panel of breast cancer cell lines, we depleted both JAK1 and JAK2 kinases (upstream regulators of STAT proteins) and found that TNBC cell lines are more likely to be dependent on JAK2 than JAK1 for survival." (PMID 30777101, 2019). "To confirm the correlation, we assessed the presence of TILs in the surrounding stroma of 57 breast cancer cases in which we had already tested the JAK1 mRNA." (PMID 31790361, 2019). "In conclusion, JAK1 mRNA levels were correlated with prognosis and immune infiltrating levels in breast cancer." (PMID 31790361, 2019). "JAK1 mRNA levels correlated with prognosis and immune infiltrating levels in breast cancer, indicating that it can be used as a prognostic biomarker." (PMID 31790361, 2019). "The JAK1 mRNA levels in 57 breast cancer tissues were further correlated with the clinicopathological characteristics of breast cancer." (PMID 31790361, 2019).
breast cancer (continued). "The Oncomine database analysis revealed that JAK1 mRNA expression of breast cancer increased in 1 data set and decreased in 7 data sets compared to the normal tissues." (PMID 31790361, 2019). "High JAK1 expression was associated with increased survival in both TNM I-II (P = 0.038) and TNM III-IV (P = 0.013) breast cancer patients." (PMID 31790361, 2019). "In luminal breast cancer, JAK1 expression levels were positively correlated with infiltrating levels of CD8+ T cells, CD4+ T cells, macrophages, neutrophils, and dendritic cells." (PMID 31790361, 2019). "We found that JAK1 mRNA levels were statistically significantly lower in the low TILs group compared with high TILs group in our breast cancer patient cohort." (PMID 31790361, 2019). "JAK1 expression was evaluated using the PrognoScan and was notably found to significantly impact prognosis in breast cancer." (PMID 31790361, 2019). "Previously, gain-of-function mutations have been reported in JAK1 or JAK3 in some neoplasms, leukemia, breast cancer, lung cancer, hepatocellular carcinoma, and NK-lymphoma cells." (PMID 30123428, 2018). "The remaining four CNVRs overlapped with genes ZFP14, JAK1, LPA, PDGFRA and were also associated with RFS in breast cancer." (PMID 29116104, 2017). "A number of the identified CD47-dependent genes including MBP1, TBL1XR1, girdin, cyclin D1, CDC27, SPAG9, and JAK1 have reported functions in breast cancer progression." (PMID 26840086, 2016). "Intriguingly, we observed that the Jak1/STAT3 pathway was significantly activated in trastuzumab-treated EGFRvIII+HER2+ breast cancer cells." (PMID 26474285, 2015). "Jak1 was reported to be activated by PRL signaling in human breast cancer lines and cooperate with Jak2 to enhance signaling pathways downstream of PRL receptors, including Stat5, Stat3 and Erk activation." (PMID 23758962, 2013). "Inhibition of Janus kinase 1 activation has been observed in human breast cancer, and its expression was downregulated by -3.5 fold in SRC1-/- mammary tumors." (PMID 21080969, 2010). "Recent report has shown that CDDO-Me inhibits activation of the JAK/Stat3 pathway by forming adducts with both JAK1 and Stat3 in human cervical and breast cancer cells." (PMID 20459702, 2010). "JAK1 also interacts with DPYSL2 to promote breast cancer cell migration." (PMID 41511940, 2026). "JAK1 is essential for IL-6-class inflammatory cytokine signaling and plays a critical role in metastatic cancer progression in breast cancer and may provide a similar role in ovarian endometrioid carcinoma." (PMID 40981433, 2025). "Interestingly, we revealed that hub gene JAK1, with favorable prognosis value in NB, was abundant in oncological research value, which has been proved as oncogene in breast cancer and non-small cell lung cancer." (PMID 39703515, 2024). "Additionally, we have identified the deletion of EGR3 to be a crucial genetic alteration in canine mammary cancer, which regulates the JAK1/STAT3 signaling pathway." (PMID 38338065, 2024). "In various tumors, including colorectal, lung, and breast cancers, JAK1/2-STAT3 is overactivated." (PMID 38336839, 2024). "Serotonin has already been shown to affect the proliferation and metabolism of breast cancer cells by triggering two distinct signaling pathways: Jak1/STAT3 which boosts glycolysis by upregulating PKM2, and adenylyl cyclase/PKA which promotes mitochondrial biogenesis." (PMID 37046602, 2023). "Similarly, JAK1 is activated by PRLR signaling in a subset of breast cancers, while underexpression of JAK1 is needed for the invasion of immune response." (PMID 35620468, 2022). "Importantly, we explored the mechanism of how DOR activation promotes breast cancer progression, finding strong induction of oncogenic JAK1/2-STAT3 signaling and epithelial-mesenchymal transition (EMT) markers." (PMID 33465556, 2021). "It has also been shown that JAK1 plays an important role in STAT3 activation in breast cancer." (PMID 34066153, 2021).
breast cancer (continued). "Importantly, we found that opioid exposure failed to induce classical migration pathways such as MAPK/ERK, TGF-β/SMAD2/3 or WNT/β-Catenin in breast cancer cells, but activated the migratory JAK1/2–STAT3 axis." (PMID 33465556, 2021). "For example, CD70, which is highly expressed in glioma, can promote macrophage infiltration into a tumor, and JAK1 was shown to be positively correlated with the infiltration of various immune cells in breast cancer, such as CD8+ T cells and dendritic cells, etc.." (PMID 34098960, 2021). "Notably, STAT3 knockdown or upstream inhibition through the JAK1/2 kinase inhibitor ruxolitinib prevented opioid-induced breast cancer cell metastasis and migration in vitro and in vivo." (PMID 33465556, 2021). "Finally, this proof-of-principle study provides evidence that the JAK1 tyrosine kinase plays a central role in the constitutive activation of STAT3 in KRAS-transformed mammary cancer cells." (PMID 34675248, 2021). "We showed that serotonin, through 5-HTR2A/C, interferes with breast cancer cells proliferation and metabolism by triggering two distinct signalling pathways: Jak1/STAT3 that boosts glycolysis through upregulation of PKM2, and adenylyl cyclase/PKA that enhances mitochondrial biogenesis." (PMID 31819176, 2020). "Of these, JAK1 is known for its key role in breast cancer progression." (PMID 32293263, 2020). "By contrast, the expression of JAK1 was significantly decreased in bladder carcinoma, breast carcinoma, colon adenocarcinoma, chromophobe renal cell carcinoma, liver hepatocellular carcinoma, LUAD, lung squamous cell carcinoma, prostate cancer, and adenocarcinoma of the rectum." (PMID 33323549, 2020). "Here, we report a study supporting the role of JAK1 in breast cancer." (PMID 31790361, 2019). "Survival analysis of JAK1 mRNA in breast cancer patients (the PrognoScan)." (PMID 31790361, 2019). "Moreover, we also investigated the correlation of JAK1 mRNA levels with clinicopathological characteristics and tumor-infiltrating immune cells of breast cancer patients." (PMID 31790361, 2019). "In addition, a PHS treatment reduces the interaction of EGFR with the downstream JAK1/STAT3 signaling network in breast cancer cells." (PMID 29100426, 2017). "JAK1 is a protein tyrosine kinase involved in the response to interferons; recently the closely related JAK2 family member was found to be associated with improved outcome in breast cancer." (PMID 27469239, 2016). "Our earliest studies determined whether the ERBB1/2/4 inhibitor lapatinib interacted with the JAK1/2 inhibitor ruxolitinib to kill breast cancer cells." (PMID 27379204, 2016). "However, we have reported that in human breast cancer cell lines Jak1 is also recruited in a Jak2-dependent manner for maximal PRL-activation of Stat5 and other signaling mediators." (PMID 23758962, 2013). "A DriverNet prediction not identified by the Frequency approach included JAK1 (p = 0, ranked 13th, mutated in one case), which plays a key role in prolactin signaling, which is implicated in breast cancer." (PMID 23383675, 2012). "Therefore, high JAK1 mRNA being a good prognostic marker in breast cancer patients may be due to the importance of JAK1 in immune system function." (PMID 31790361, 2019). "The Janus kinase 1 (JAK1)/STAT1/IRF1 signaling pathway, which is activated by the binding of IFN-γ to IFN receptors, prevents mammary cancer formation by maintaining growth control." (PMID 41567365, 2026). "The authors show that the combination of HDACi with JAK1 or BRD4 inhibition sensitises breast cancer cells to HDACi, and suggest this combination treatment strategy for the treatment of breast cancer." (PMID 40011240, 2025). "In this work, we developed an in vitro assay to trigger dormancy in HER2-amplified human breast cancer cells and studied the induction of CSC features, as well as the function of JAK1 and STAT3, components of the IL-6–STAT3 axis." (PMID 40430044, 2025).